WNT7A (Wnt family member 7A)
Description:
Ligand for members of the frizzled family of seven transmembrane receptors that functions in the canonical Wnt/beta-catenin signaling pathway (By similarity). Plays an important role in embryonic development, including dorsal versus ventral patterning during limb development, skeleton development and urogenital tract development. Required for central nervous system (CNS) angiogenesis and blood-brain barrier regulation. Required for normal, sexually dimorphic development of the Mullerian ducts, and for normal fertility in both sexes (By similarity). Required for normal neural stem cell proliferation in the hippocampus dentate gyrus (By similarity). Required for normal progress through the cell cycle in neural progenitor cells, for self-renewal of neural stem cells, and for normal neuronal differentiation and maturation (By similarity). Promotes formation of synapses via its interaction with FZD5 (By similarity).
Synonyms: Wnt-7a; SANTOS
Tractability: Small molecule: a structure with a bound ligand is known. Antibody: UniProt places it where antibodies can reach, with high confidence; its Gene Ontology location is reachable by antibodies, with high confidence; UniProt predicts a signal peptide or a membrane-spanning region. PROTAC: its protein half-life has been measured.
Gene: Protein-coding gene on chromosome 3 (13,816,258 to 13,880,071, reverse strand). Ensembl gene ENSG00000154764.
Subcellular location: Secreted, extracellular space, extracellular matrix; Secreted
Pathways (Reactome):
Signal Transduction: Class B/2 (Secretin family receptors); WNT ligand biogenesis and trafficking
Gene Ontology:
Molecular function: cytokine activity; protein binding; receptor ligand activity; signaling receptor binding; frizzled binding
Biological process: canonical Wnt signaling pathway; cartilage condensation; cell proliferation in forebrain; cellular response to transforming growth factor beta stimulus; chondrocyte differentiation; dendritic spine morphogenesis; embryonic axis specification; embryonic digit morphogenesis; embryonic forelimb morphogenesis; embryonic hindlimb morphogenesis; negative regulation of neurogenesis; positive regulation of DNA-templated transcription; positive regulation of epithelial cell proliferation involved in wound healing; positive regulation of excitatory postsynaptic potential; positive regulation of excitatory synapse assembly; positive regulation of protein metabolic process; positive regulation of synapse assembly; positive regulation of transcription by RNA polymerase II; regulation of presynapse assembly; secondary palate development; stem cell development; Wnt signaling pathway, planar cell polarity pathway; wound healing, spreading of epidermal cells; axonogenesis; cell fate commitment; and 22 more
Cellular component: extracellular region; glutamatergic synapse; endocytic vesicle membrane; endoplasmic reticulum lumen; extracellular exosome; Golgi lumen; plasma membrane; cell surface; extracellular matrix; presynapse; Schaffer collateral - CA1 synapse
Genetic constraint (gnomAD): Loss-of-function variants: 17 observed, 31.6 expected, observed/expected ratio (o/e) 0.54, 90% interval 0.37 to 0.81. The upper end of that interval is the gene's LOEUF score, 0.81, which puts it in group 3 of 6, group 1 being the genes least tolerant of losing a copy. Missense variants: 411 observed, 514.22 expected, observed/expected ratio (o/e) 0.8, 90% interval 0.74 to 0.87. Synonymous variants: 190 observed, 206.07 expected, observed/expected ratio (o/e) 0.92, 90% interval 0.82 to 1.04.
Homologues: Orthologues: chimpanzee WNT7A (100% identical), dog WNT7A (99% identical), macaque WNT7A (99% identical), guinea pig WNT7A (99% identical), mouse Wnt7a (99% identical), pig WNT7A (99% identical), rat Wnt7a (99% identical), rabbit WNT7A (93% identical), tropical clawed frog wnt7a (88% identical), zebrafish wnt7aa (86% identical), zebrafish wnt7ab (81% identical), Drosophila melanogaster Wnt2 (48% identical), and 5 more. Paralogues in human: WNT7B (77% identical), WNT2B (49% identical), WNT4 (46% identical), WNT2 (45% identical), WNT5B (44% identical), WNT5A (44% identical), WNT3 (43% identical), WNT16 (42% identical), WNT3A (42% identical), WNT10A (41% identical), WNT10B (39% identical), WNT6 (38% identical), and 6 more.
Diseases named in the same sentence as WNT7A in open-access papers:
WNT7A is named in the same sentence as 120 diseases in open-access papers, as found by Europe PMC text mining. Sharing a sentence is not in itself a finding about the gene and the disease. The quoted sentences say what the papers report.
lung carcinoma (31 papers, 2006 to 2024). "Considering that lung cancers are predominantly epithelial cell-derived, our data highlights the importance of Wnt7a expression in the lung epithelium and its loss as a major contributing factor for carcinogenesis." (PMID 25728679, 2015). "While frequent loss of Wnt7a mRNA was demonstrated in some studies in lung cancer cell lines and primary tumours, elevated levels of Wnt1 and Wnt2 have been reported in non small cell lung cancer." (PMID 16438732, 2006). "WNT7a not only induces cellular senescence by inactivating S phase kinase-associated protein 2 in a β-catenin-independent manner, but also inhibits the progression of lung cancer by activating E-cadherin expression in a β-catenin-dependent manner." (PMID 37486552, 2023). "The loss of WNT7A is a major contributing factor for increased lung cancer tumorigenesis." (PMID 30453959, 2018). "E-cadherin induction by Wnt/β-catenin signaling is an evolutionarily conserved pathway operative in lung cancer cells, and loss of Wnt7A expression may be important in lung cancer development or progression due to its effects on E-cadherin." (PMID 25632963, 2015). "E-cadherin induction by Wnt/β-catenin signaling is an evolutionarily conserved pathway operative in lung cancer cells, and loss of Wnt7A expression may be important in lung cancer development or progression through its effects on E-cadherin." (PMID 25632963, 2015). "As such, the loss of Wnt7a could have a major impact on the development of lung cancer, especially when combined with the upregulation of an influential oncogene." (PMID 22403725, 2012). "WNT7A is closely related to the prognoses of multiple solid tumors, such as pancreatic cancer, oral squamous cell carcinoma, and lung cancer." (PMID 33680915, 2020). "Conversely, we found that the Wnt family member Wnt7a, recently shown to have a tumor-suppressive role in lung cancer by inducing cellular senescence, was significantly suppressed in G1, G3, and G5 spheres relative to the parental cell counterparts." (PMID 31001473, 2019). "As a member of Wnt family, WNT7A has been investigated in several types of cancer including ovarian cancer, cervical cancer, endometrial cancer, lung cancer etc.12–14." (PMID 30361522, 2018). "The Wnt family member 7A (WNT7A) gene, as a member of WNT gene family, encodes secreted signaling proteins and is related to suppressing human lung cancer progression." (PMID 28356085, 2017). "Frizzled-9 is also activated in Wnt-7a signaling and functions as a tumor suppressor in lung cancer." (PMID 23815780, 2013). "Both Wnt-1 and Wnt-2 are up-regulated in non-small cell lung cancer (NSCLC), whereas Wnt-7a is down-regulated in most lung cancer cell lines and tumor tissues." (PMID 23815780, 2013). "This study investigates the important issue of how Wnt7a expression is lost and how its expression can be restored in an effort to treat lung cancer." (PMID 22403725, 2012). "The upregulation of WNT7A has been previously reported in different types of cancer, including colorectal cancer, lung cancer, and ovarian cancer, suggesting that WNT7A may be a common oncogenic factor in cancer." (PMID 38246919, 2024). "WES analysis of TCS627 did indicate a mutation in WNT7A, a factor that can activate the canonical and non-canonical Wnt pathways described as a tumor suppressor in lung cancer but also as an oncogene in ovarian, breast and brain tumors." (PMID 38201285, 2023). "Additionally, the putative targets of miR-497-5p including PSMD7, CCND3, SMURF2, and WNT7A increase chemoresistance in gastric cancer, acute myeloid leukemia, lung cancer and OSCC, respectively." (PMID 36703917, 2022). "Actually, WNT7A functions as an EMT inhibitor in lung cancer." (PMID 33618713, 2021). "Wnt7a was also inactivated in lung cancer, and restoration of Wnt7a could accelerate cell senescence." (PMID 31886205, 2019). "On the other hand, the restoration of Wnt7a could inhibit the proliferation in lung cancer and cervical cancer." (PMID 31886205, 2019).
lung carcinoma (continued). "However, it is reported that the expression of WNT7A reduced in cervical cancers, lung cancer and clear cell renal carcinomas." (PMID 30361522, 2018). "Apparent physiologic levels of Wnt7A positively regulate E-cadherin expression in lung cancer." (PMID 25632963, 2015). "Thus compounds that can induce Wnt7a expression, or function similarly to Wnt7a, would have a great potential for pro-senescence therapy in lung cancer." (PMID 25728679, 2015). "Our data would also suggest that identifying pharmacological activators of Wnt7a/Fzd9 pathway and/or hsa-miR29b might have utility in the treatment of lung cancer." (PMID 23862015, 2013). "In strong contrast, Wnt7a/Frizzled9 signaling was shown to play a protective role in lung cancer." (PMID 23862015, 2013). "In lung cancer and leukemias WNT7A was characterized as a tumor suppressor gene." (PMID 23056560, 2012). "In addition, it was reported that expression of the WNT7A gene is frequently reduced in lung cancer, and that restoration of WNT7A gene expression led to growth inhibition of NSCLC cell lines." (PMID 23056560, 2012). "In addition to the role of WNT7A observed in leukemia and lung cancer, disruptions or alterations of the WNT7A gene have also been found in oral premalignant lesions and in esophageal squamous cells." (PMID 22313908, 2012). "Moreover, the low expression of WNT7A in NSCLC might play a role in lung cancer progression through its effect on E-cadherin transcription." (PMID 35957916, 2022). "Therefore, we hypothesized that the HOXA11 gene could be regulated by the formation of a loop between Wnt5a and Wnt7a in human lung cancer." (PMID 28380439, 2017). "Thus Wnt7a appears to act as a master regulator of cellular senescence, and Wnt7a-mediated tumor-suppressive cellular senescence may represent a new class of future therapeutic treatments of lung cancer." (PMID 25728679, 2015). "Thus pro-senescence therapies using either Wnt7a or its mimic, Iloprost, might represent a new class of therapeutic treatments for lung cancer." (PMID 25728679, 2015). "Decreased levels of Wnt7a indicates that Wnt7a may function as a tumour suppressor in lung cancer." (PMID 16438732, 2006). "For example, differential expression of several WNT components including WNT1, WNT2, WNT7A, DVL3, β-CATENIN and APC, have been reported in normal lung tissues and lung cancers, particularly in NSCLC (non-small cell lung cancer)." (PMID 22846383, 2012). "FZD9 is unique among Frizzled receptors in that it does not activate oncogenic signaling pathways in lung cancer but contributes to maintenance of a normal lung epithelium and exerts tumor suppressive effects when partnered with Wnt7a or iloprost." (PMID 35149732, 2022). "WNT, TGF-beta and FGF pathways may synergistically affect HOXA1 expression, and WNT7A directly maintains expression of HOXA1, making for lung cancer recurrence." (PMID 33763449, 2020). "In contrast to what occurs in normal lung and mortal short-term bronchial epithelial cultures, Wnt7A was frequently less expressed or absent in lung cancers." (PMID 25632963, 2015). "On the other hand, downregulation of Wnt-7a has been demonstrated in the majority of NSCLC cell lines and primary tissues, suggesting that it may act as a novel tumor suppressor in lung cancer." (PMID 24348855, 2014). "We have previously identified that Wnt7a is lost in non-small cell lung cancers (NSCLC), and restoration of Wnt7a signaling in NSCLC cell lines leads to reversal of transformed phenotype, unveiling Wnt7a signaling as a novel tumor suppressive pathway in lung cancer." (PMID 24204697, 2013).
lung carcinoma (continued). "Finally, we also show that hsa-miR29b plays an important role as a tumor suppressor in lung cancer by targeting murine double mutant 2 (MDM2), revealing novel nodes for Wnt7a/Fzd9-mediated regulation of NSCLC cell proliferation." (PMID 23862015, 2013). "Finally, we show for the first time that hsa-miR29b plays an important role as a tumor suppressor in lung cancer by targeting murine double mutant 2 (MDM2), revealing novel nodes for Wnt7a/Frizzled9-mediated regulation of NSCLC cell proliferation." (PMID 23862015, 2013). "In addition, miR-127 inhibits the proliferation and invasion of gastric cancer cells via Wnt7a, inhibits ovarian cancer cell proliferation by downregulating MAPK4, regulates the NF-κB pathway through TNFAIP3, and induces epithelial-mesenchymal transformation in lung cancer." (PMID 36371182, 2022). "Additionally, recent studies have demonstrated that the combined expression of WNT7A and Frizzled 9 (Fzd9) in Non-small cell lung cancer (NSCLC) cell lines inhibits transformed growth by activating ERK5 and increasing PPARgamma activity, representing a novel tumor suppressor pathway in lung cancer." (PMID 22313908, 2012). "Unlike most WNTs, WNT7a can activate the canonical and noncanonical WNT pathways, but only exerts an anti-cancer effect on lung cancer." (PMID 37486552, 2023).
ovarian cancer (25 papers, 2009 to 2024). A primary or metastatic malignant neoplasm involving the ovary. "A significant inverse correlation in which high-expression of WNT7A and low-expression of miR-15b (n = 147 vs n = 146 of low-expression of WNT7A and high-expression of miR-15b) was associated with reduced survival rate of ovarian cancer patients by log-rank test (P = 0.0297)." (PMID 27195958, 2016). "When we evaluated the prognostic impact of WNT7A and miR-15b expression using TCGA datasets, a significant inverse correlation in which high-expression of WNT7A and low-expression of miR-15b was associated with reduced survival rates of ovarian cancer patients." (PMID 27195958, 2016). "Wnt7a expression in ovarian cancer has been associated with advanced stage and high grade, and may be a significant prognostic factor in ovarian cancer." (PMID 26343197, 2015). "Other studies using ovarian cancer cell lines showed that the expression of miR-15b represses WNT7A, a gene that promotes ovarian cancer cell proliferation." (PMID 37686596, 2023). "Wnt7a is abundant in ovarian cancer cells and can promote the proliferation, adhesion and invasion of cancer cells in cell experiments, and reduce the tumorigenicity of Wnt7a knockdown cells in vitro." (PMID 36209344, 2022). "WNT7a was reported to induce proliferation and β-catenin-mediated signaling in ovarian cancer, whereas, in leukemic cells, WNT7a reduces proliferation and has little effect on the activation of β-catenin." (PMID 36612190, 2022). "For example, SPRY4 affects cell growth as a downstream effector of Wnt7A/Fzd9 signaling in ovarian cancer, breast cancer, colorectal cancer and prostate cancer." (PMID 32581828, 2020). "Wnt7a overexpression was also found in ovary cancer and promoted tumor by inducing activation of CAFs." (PMID 31886205, 2019). "For example, WNT7A known to function as tumor-promoting in ovarian cancer is present at very low level in FT194 cells but becomes highly expressed in SKOV-3 cells where is significantly downregulated upon PAX8 silencing." (PMID 27259239, 2016). "It has been reported that WNT7A is abundantly expressed in ovarian carcinoma and is able to control cell division, adhesion and motility." (PMID 27259239, 2016). "Consistent with this interpretation, WNT7A has recently been identified as a potential early stage biomarker of human ovarian cancer." (PMID 23762861, 2013). "Meanwhile, in the OVCAR3 ovarian carcinoma cell line, stable overexpression of Wnt7a resulted in increased migration and invasive capacity." (PMID 23304155, 2012). "Further analyses of additional ovarian cancer cell lines with either overexpression or ablation of WNT7A would be needed to precisely identify its role in ovarian cancer progression." (PMID 19849863, 2009). "We therefore screened a panel of 11 ovarian cancer cell lines for expression of WNT7A compared with immortalized human ovarian surface epithelial cells (HOSE)." (PMID 19849863, 2009). "In the current study, overexpression of WNT7A in the ovarian cancer cell line OVCAR-3 resulted in increased cell migration and invasive capacity." (PMID 19849863, 2009). "Over-expression of WNT7A in an ovarian cancer cell line led to increased migration and invasive capacity." (PMID 19849863, 2009). "In vitro functional studies of one of these genes suggested a role for WNT7A in promoting migration and invasion in ovarian cancer cells." (PMID 19849863, 2009). "Far greater levels of WNT7A were observed in clones derived from independent transfections of the OVCAR-3 ovarian cancer cell line as compared to clones containing an empty vector, as demonstrated by both real time PCR (data not shown) and western blotting." (PMID 19849863, 2009). "While this is the first report of Wnt7a as a prognostic marker in breast cancer, Wnt7a has been documented to be upregulated in malignant as compared with borderline or benign ovarian tumours and to promote tumour growth in in vivo ovarian cancer models." (PMID 26777421, 2016).